NUDT4B (nudix hydrolase 4B)
Description:
Cleaves a beta-phosphate from the diphosphate groups in PP-InsP5 (diphosphoinositol pentakisphosphate), PP-InsP4 and [PP]2-InsP4 (bisdiphosphoinositol tetrakisphosphate), suggesting that it may play a role in signal transduction. Also able to catalyze the hydrolysis of dinucleoside oligophosphate Ap6A, but not Ap5A. The major reaction products are ADP and p4a from Ap6A. Also able to hydrolyze 5-phosphoribose 1-diphosphate. Does not play a role in U8 snoRNA decapping activity. Binds U8 snoRNA.
Synonyms: DIPP-2B; NUDT4P1
Gene: Protein-coding gene on chromosome 1 (148,748,774 to 148,752,415, forward strand). Ensembl gene ENSG00000177144.
Subcellular location: Cytoplasm
Subcellular location (Human Protein Atlas): Cytosol
Gene Ontology:
Molecular function: protein binding; bis(5'-adenosyl)-hexaphosphatase activity; bis(5'-adenosyl)-pentaphosphatase activity; diphosphoinositol-polyphosphate diphosphatase activity; endopolyphosphatase activity; hydrolase activity; pyrophosphatase activity
Biological process: adenosine 5'-(hexahydrogen pentaphosphate) catabolic process; diadenosine hexaphosphate catabolic process; diadenosine pentaphosphate catabolic process; diphosphoinositol polyphosphate metabolic process
Cellular component: cytoplasm; nucleus
Homologues: Orthologues: chimpanzee NUDT4 (100% identical), macaque NUDT4 (99% identical), dog NUDT4 (98% identical), mouse Nudt4 (96% identical), rat Nudt4 (95% identical), tropical clawed frog nudt4 (78% identical), zebrafish nudt4a (77% identical), zebrafish nudt4b (75% identical), Drosophila melanogaster Aps (53% identical). Paralogues in human: NUDT4 (99% identical), NUDT11 (82% identical), NUDT10 (82% identical), NUDT3 (72% identical).
Diseases named in the same sentence as NUDT4B in open-access papers:
NUDT4B is named in the same sentence as 5 diseases in open-access papers, as found by Europe PMC text mining. Sharing a sentence is not in itself a finding about the gene and the disease. The quoted sentences say what the papers report.
cancer (1 paper, 2022). A tumor composed of atypical neoplastic, often pleomorphic cells that invade other tissues. "We found 5 primary regulator genes (EIF4E1B, METTL1, NUDT11, NUDT10 and NUDT4B) were differential expressed in more than 15 cancer types." (PMID 36092891, 2022).
NUDT4B also shares sentences with these, for which no sentence is quoted: tumor (3 papers); glioma (1); pancreatic adenocarcinoma (1); thymoma (1).